LPAR6 (lysophosphatidic acid receptor 6)
Diseases named in the same sentence as LPAR6 in open-access papers (continued):
Sharing a sentence is not in itself a finding about the gene and the disease.
tumor (continued). "Interestingly, the rest of the LPARs (LPAR1, LPAR3–5) are decreased in the HCC liver as compared to adjacent normal tissue, suggesting that LPAR2 and LPAR6 are probably expressed in the tumor whereas the rest LPARs are expressed in the surrounding microenvironment." (PMID 31652837, 2019). "Inflammatory signaling pathways were elevated, particularly in high-LPAR6-expressing tumors in all cohorts, and in tumor suppressor pathways apart from DNA repair pathways in high-LPAR1-, LPAR4-, and LPAR6-expressing tumors." (PMID 37372960, 2023). "The LPAR6 expression level of LUAD and LUSC are all significantly negatively related to tumor purity." (PMID 34769557, 2021). "LPA is a kind of lipid that is involved in the proliferation of tumor cells via its G-protein coupled (GPC) receptors and one of their receptors—LPAR6—is the latest identified receptor of LPA." (PMID 34769557, 2021). "Especially in the tumor tissue of LUAD, both IRF5 and NOS2 show significant correlations with LPAR6 expression and PTGS2 shows a significant correlation with LPAR6 expression in the tumor tissue." (PMID 34769557, 2021). "With both tumor cells and TAM expressing similar levels of LPAR1 and LPAR2, LPAR3 was predominantly expressed in tumor cells, while LPAR5 and LPAR6 were selective for TAM." (PMID 32397679, 2020). "In tumor cells, LPAR1, LPAR2, and LPAR3 are the major subtypes, while LPAR5 and LPAR6 are expressed only at very low levels in a subset of patients, if at all." (PMID 30353652, 2019). "The repression affects known tumor or metastasis suppressor genes, such as TRIM 29, ACVR1B, and LPAR6, and the sestrins, SESN1 and SESN3; however, in our analyses, ACVR1B, LPAR6, and sestrins were not validated by the qNPA method." (PMID 22276141, 2012). "So here we selected the cancer types in which LPAR6 expression levels have a significant negative correlation with tumor purity in TIMER and a significant correlation with prognosis." (PMID 34769557, 2021). "A pairwise analysis of tumor and non-tumor tissue from a big Chinese cohort of CHB patients with HCC showed that ATX is significantly upregulated in tumor compared to non-tumor tissue and the same applies to LPAR6." (PMID 31652837, 2019). "LPA in ascites apparently targets tumor cells and TAMs via specific receptors, since LPAR1 and LPAR2 are expressed at similar levels by both cell types, LPAR3 is selective for tumor cells, LPAR5 and LPAR6 for TAMs." (PMID 27215396, 2016). "Lastly, LPAR6 was highly expressed on CD8+ T cells irrespective of tumor model." (PMID 37655662, 2023).
cancer (22 papers, 2012 to 2025). A tumor composed of atypical neoplastic, often pleomorphic cells that invade other tissues. "LPAR1 and LPAR4 were highest in cancer-associated fibroblasts, while LPAR6 was highest in endothelial cells, and LPAR2 was highest in cancer epithelial cells." (PMID 37372960, 2023). "LPAR1 and LPAR4 expression levels were highest in cancer-associated fibroblasts (CAFs), while most of the LPAR6 expression determined was in endothelial cells followed by myeloid cells and CAFs." (PMID 37372960, 2023). "LPAR6 was first reported in hypotrichosis simplex and afterwards was implicated in the initiation and progression of cancer." (PMID 34510318, 2022). "The association between LPAR6 and immune infiltrates of various types of cancer were investigated via TIMER." (PMID 34769557, 2021). "An interaction network of LPAR6 was constructed to determine potential interactions between LPAR6 and other cancer-associated proteins." (PMID 34769557, 2021). "Further, a higher LPAR6 expression level was associated with better prognosis potential in some other types of cancer." (PMID 34769557, 2021). "In this study, we announced that different mRNA expression levels of LPAR6 are associated with the prognostic potential in various types of cancer." (PMID 34769557, 2021). "In this study, we offered a potential explanation for the mechanism that why the mRNA expression level and protein of LPAR6 correlates with immune infiltration level and associates to a better prognostic potential in some specific types of cancer, especially in LUAD." (PMID 34769557, 2021). "We analyzed whether the mRNA expression level of LPAR6 was associated with the prognosis specific across cancer patient cohorts." (PMID 34769557, 2021). "Current study provides a backbone for understanding structural and functional insights of LPAR6 and findings of this study may be helpful in designing novel therapeutic targets for the treatment of cancers caused by elevated LPAR6 expression." (PMID 29211777, 2017). "Through analysis using the TIMER2.0 database, we found that, compared to corresponding normal tissues, LPAR6 expression was downregulated in 10 different cancer types and significantly upregulated in 8 other cancers." (PMID 40362442, 2025). "Although LPAR6 remains understudied, its involvement in cancer progression and survival and early pregnancy adaptation in animals highlights its biological significance." (PMID 41199770, 2025). "As a sub-family of GPCRs, LPAR6 has the potential to be targeted for disease therapy; it exhibits different roles in different organs affected by cancer." (PMID 34510318, 2022). "Given the correlation of the mRNA expression level of LPAR6 with immune-infiltration level in diverse types of cancer, we investigated the distinct types of cancer in which LPAR6 was correlated with prognosis and immune-infiltration." (PMID 34769557, 2021). "CD8A, a crucial protein on T cells surface, is highly correlated with LPAR6 expression in LUAD which are types of cancers with better prognosis." (PMID 34769557, 2021). "In this work, we determined the LPAR6 expression levels and constructed a systematic prognostic landscape in various types of cancer using independent datasets and 33 type cancers of TCGA data in online database." (PMID 34769557, 2021). "LPAR6 is the most recently determined G-protein-coupled receptor of the lysophosphatidic acid receptor, and very few of studies have demonstrated the performance of LPAR6 in cancers." (PMID 34769557, 2021). "To evaluate the mRNA expression level of LPAR6 in cancers, we studied the levels of LPAR6 expression employing the RNA-Seq datasets in the TCGA." (PMID 34769557, 2021). "The variation expression level of LPAR6 between cancer and normal tissues was determined in many cancer types." (PMID 34769557, 2021).
cancer (continued). "Thirdly, different correlation patterns have been found between the mRNA expression level of LPAR6 and the regulation of markers of T helper cells (Th1, Th2, Th17 and Tfh) in these different cancers." (PMID 34769557, 2021). "This supports the argument that the LPAR6 expression levels are important contributors to human malignancies and indicating the prognostic potential of specific types of cancer." (PMID 34769557, 2021). "Here, we investigated the mRNA expression level of LPAR6 and the correlation with prognosis patterns of cancer patients in databases using bioinformatics tools." (PMID 34769557, 2021). "We analyzed the correlations of LPAR6 mRNA expression with the immune-infiltration levels in nearly 40 types of cancer." (PMID 34769557, 2021). "Another crucial aspect is that the mRNA expression level of LPAR6 is correlated with diverse immune-infiltration levels in cancer, particularly in LUAD." (PMID 34769557, 2021). "LPAR6 knockdown caused the formation of larger colonies and enhanced motility in colon DLD1 and HCT116 cancer cells." (PMID 34209775, 2021). "They identified α-BuIA as strongly binding to LPAR6, making it a good candidate for investigation and refinement as a possible anti-cancer drug." (PMID 30832207, 2019). "Therefore, increasing the expression of LPAR6 receptors and developing LPAR6 agonists will undoubtedly provide a new approach for adjunctive cancer therapy." (PMID 40362442, 2025). "In conclusion, these findings suggest that enhancing LPAR6 expression or developing LPAR6 agonists may offer a promising therapeutic strategy for adjuvant cancer treatment." (PMID 40362442, 2025). "In pancreatic cancer, LPAR6 knockdown also inhibited cancer invasion and colony formation." (PMID 34209775, 2021). "The role of LPAR6 in various cancer types should be further characterized in the future." (PMID 34209775, 2021). "So, in this study, we determined whether the expression level of LPAR6 correlates with the immune-infiltration levels in various types of cancer." (PMID 34769557, 2021). "Reports regarding LPAR6 in cancer are relatively limited compared with other LPARs." (PMID 34209775, 2021). "These vary in the mRNA expression levels of LPAR6 in different types of cancer among various databases might be a reflection in data collection approaches and underlying mechanisms involved in different biological properties." (PMID 34769557, 2021). "In addition to microarray analysis data of LPAR6, the RNA-Seq was also used to analyze the prognosis of LPAR6 in various types of cancers via the same database." (PMID 34769557, 2021). "The effects of LPAR6 (P2Y5) in cancers are uncertain and require further investigation." (PMID 32887262, 2020). "LPAR6 mediates cell viability by possessing pro-survival activity in the cancer cells." (PMID 29211777, 2017). "However, LPAR6 can, by contrast, be a negative regulator in different cancers." (PMID 34209775, 2021). "Currently, research on the role of LPAR6 in HCC and related cancers is still limited, and further in-depth studies are needed to explore the potential and mechanisms of this receptor." (PMID 40362442, 2025). "For anti-cancer CD8+ cells, enrichment was only significantly correlated with high-LPAR5- and LPAR6-expressing tumors (all p < 0.001)." (PMID 37372960, 2023). "As mentioned in the results section, PLD network involves proteins such as LPAR4, LPAR6, HCRTR1, and GRM5, as well as pathways like EGF/EGFR SP, which their roles have been proven in initiation and progression of several cancers." (PMID 29062084, 2017). "Thus LPAR6 may serve as a promising therapeutic target for the treatment of various cancer types." (PMID 29211777, 2017). "Epithelial cell (primarily cancer cells) composition was significantly enriched in high-LPAR2 and -LPAR3-expressing tumors in all three cohorts (all p < 0.001) but decreased in high-LPAR1, -LPAR5, and -LPAR6-expressing tumors (all p < 0.05)." (PMID 37372960, 2023).
cancer (continued). "However, none of these gene markers was significantly correlated with the LPAR6 expression level in LUSC and other cancer with poor prognosis." (PMID 34769557, 2021). "IFN-g is a Th1 cytokine with both pro- and anti-cancer properties which are highly correlated with LPAR6 expression in LUAD, whereas it did not demonstrate significant correlations in LUSC." (PMID 34769557, 2021). "In addition, the expression level of LPAR6 has significant correlations with infiltrating levels of CD8+ T cells in 24 types of cancer, CD4+ T cells in 26 types of cancer, neutrophils in 33 types of cancer, macrophages in 20 types of cancer and dendritic cells in 21 types of cancer." (PMID 34769557, 2021).
LPAR6 also shares sentences with these, for which no sentence is quoted: colon carcinoma (5 papers); pancreatic cancer (5); glioma (3); hypotrichosis (3); bladder cancer (2); hypotrichosis 8 (2); Obesity (2); achromatopsia (1); acute myeloid leukemia (1); adenoma (1); adenomyosis (1); adrenocortical carcinoma (1); Alopecia universalis (1); asthma (1); astrocytomas (1); Carvajal syndrome (1); ectodermal dysplasia (1); endometriosis (1); Familial Woolly Hair Syndrome (1); follicular lymphoma (1); gastric cancer (1); glioblastoma (1); hypotrichosis 4 (1); hypotrichosis 6 (1); leukemia (1); lung squamous cell carcinoma (1); lymph node metastasis (1); lymphoma (1); mesenchymal tumors (1); metabolic disease (1).
A further 9 diseases each share a sentence with LPAR6 in 1 paper.